RIPK4 (receptor interacting serine/threonine kinase 4)
Diseases named in the same sentence as RIPK4 in open-access papers (continued):
Sharing a sentence is not in itself a finding about the gene and the disease.
melanoma (continued). "Our study fills this gap because it is the first to reveal the functional role of RIPK4 in melanoma." (PMID 34768934, 2021). "Estimation of single WM226.4 cell trajectories by time-lapse video microscopy along with the results of wound healing assay demonstrated the reduced motility and displacement of melanoma cells after the ectopic RIPK4 down-regulation." (PMID 34768934, 2021). "On the other hand, our data show that RIPK4 activity contributes to the invasive potential of melanoma cells." (PMID 34768934, 2021). "PMA increased PKC1β level and reduced RIPK4 level in WM266.4 melanoma cells after 12–48 h of treatment, and concomitantly inhibited the WM266.4 cell motility." (PMID 34768934, 2021). "This role is illustrated by (i) the relatively high levels of RIPK4 in metastatic melanoma cell lineages and tumor specimens and (ii) the reduction of motility of melanoma cells by RIPK4 down-regulation." (PMID 34768934, 2021). "To this end, we used transcriptomic analyses of RIPK4 expression levels in melanoma specimens from clinical trials, IHC in melanoma biopsies, and protein level in patient-derived and commercially available melanoma cell lines." (PMID 34768934, 2021). "This heterogenous expression, together with very low level of RIPK4 in melanocytes, indicates that the role of this kinase in melanoma is context-dependent." (PMID 34768934, 2021). "Using patient-derived cell lines and clinical samples, we show that RIPK4 is expressed in melanomas at different levels." (PMID 34768934, 2021). "Expression of RIPK4 in melanoma cells at the mRNA and protein levels was higher in melanoma cells than in normal melanocytes." (PMID 34768934, 2021). "A similar difference in staining was seen in xenografts obtained from melanoma cell lines with high levels of the RIPK4 kinase such as A375, WM266.4 or DMBC21." (PMID 34768934, 2021). "This revealed similar RIPK4 mRNA levels (normalized to the log2 value) in the melanoma biopsies from primary and metastatic tumors, similarly to IHC staining data in this study." (PMID 34768934, 2021). "Our data also show that IκBα/p65-dependent signaling remains under the control of RIPK4/PKC-1β in both melanoma cell lines." (PMID 34768934, 2021). "The results indicate that RIPK4 contributes to melanoma invasive potential in a lineage-specific/NF-κB-dependent manner." (PMID 34768934, 2021). "Before treatment, a clear positive correlation was observed between the level of RIPK4 and phosphorylation of p65 in both cell lines and patient-derived melanoma cell lines." (PMID 34768934, 2021). "We also observed differences in the sensitivity of melanoma cell lines to RIPK4-dependent signaling." (PMID 34768934, 2021). "It appears that further studies are needed to fully assess the long-term consequences of RIPK4 involvement in the regulation of melanoma phenotype and microevolution of melanoma cells." (PMID 34768934, 2021). "To preliminarily assess the significance of RIPK4 in melanoma development, we performed immunohistochemical (IHC) staining on primary and metastatic melanoma tissues, including samples from the same patients." (PMID 34768934, 2021). "These analyses further confirmed the role of RIPK4 in the regulation of melanoma motile capacity in vitro and showed the functional links between RIPK4- and PKC-dependent signaling in WM266.4 cells." (PMID 34768934, 2021). "Differential interplay between PKC and RIPK4 expression in discrete melanoma cells participates in this process." (PMID 34768934, 2021). "Various levels of RIPK4 were detected in melanoma cells, from slightly above levels in melanocytes of DMBC11, DMBC12 and WM115 cell lines to highly elevated values in DMBC28, DMBC29 and WM266.4 cell lines." (PMID 34768934, 2021). "Our mechanistic studies demonstrated that the function of RIPK4 in melanoma cells is predominantly executed through the activation of NF-κB signaling." (PMID 34768934, 2021).
melanoma (continued). "To address the role of RIPK4 in melanoma progression more directly, we further investigated the effects of ectopic RIPK4 down-regulation on the phenotype of highly invasive WM266.4 melanoma cells." (PMID 34768934, 2021). "We also found that RIPK4 expression was up-regulated in xenografts when compared to original melanoma cell lines." (PMID 34768934, 2021). "Further analyses of the consequences of RIPK4 down-regulation in melanoma cells revealed its clear impact on the invasive potential manifested by decreased transmigratory potential and motility of WM266.4 cells, which was also observed in A375 cells." (PMID 34768934, 2021). "Together, our results establish RIPK4 as a critical regulator of melanoma invasion and metastasis." (PMID 41660747, 2026). "Furthermore, increased serum TNF-α levels and the correlation of RIPK4 with NF-κB were revealed in melanoma patients." (PMID 38656555, 2024). "Therefore, studies investigating the functional role of RIPK4 in melanoma cells are important for a more comprehensive understanding of anti-melanoma treatment using BRAFi, as well as for elucidating the biology of this tumor." (PMID 38656555, 2024). "It appears that RIPK4 kinase may regulate the adhesive properties of melanoma cells by involving in the p38/EKL-1 axis." (PMID 38656555, 2024). "Variable levels of RIPK4 in melanoma cells, ranging from very high to almost negligible, may reflect different sensitivities to CisPt." (PMID 39766280, 2024). "Such a result suggests that not only RIPK4 but also other features, such as BRAF mutation status, may influence the sensitivity of melanoma cells to cisplatin." (PMID 39766280, 2024). "Our previous studies strongly indicate that RIPK4 plays an oncogenic role in melanoma." (PMID 39766280, 2024). "Notably, our previous observations indicated that RIPK4 silencing led to alteration in focal contact architecture, resulting in reduced cell movement of melanoma cells." (PMID 38656555, 2024). "First, we confirmed that the RIPK4 structure and sequence of RIPK4 is similar to both the BRAF protein and its mutant form and then verified that the BRAFV600 E or K mutation does not affect the expression of the RIPK4 protein in melanoma specimens." (PMID 36765875, 2023). "We showed that the level of RIPK4 is increased in some melanoma cells that may represent the invasive front of the tumor, and that regulates PKC/NFkappaB signaling." (PMID 36765875, 2023). "Additionally, we tested the impact of RIPK4 downregulation and upregulation/overexpression on the RIPK4/PEPB1 axis and the RAS/RAF/MEK/ERK and FAK/AKT pathways in melanoma cells carrying V600E and V600D mutations." (PMID 36765875, 2023). "Furthermore, BRAFi inhibited ERK1/2 activity and lowered RIPK4 protein levels in BRAF-mutated melanoma cells (A375 and WM266.4), while in wild-type BRAF cells (BLM and LoVo), both inhibitors decreased the level of RIPK4 and enhanced ERK1/2 activity." (PMID 36765875, 2023). "Thus, RIPK4/NF-κB-dependent signaling axis at least partly sustains mesenchymal phenotype of melanoma cells as additionally revealed by morphological shifts of WM266.4 cells towards an epithelioid phenotype upon RIPK4 inhibition." (PMID 34768934, 2021). "These are manifested by less pronounced effects of RIPK4 silencing on morphology and expression of pro-invasive markers in A375 cells than in WM266.4 cells, and by differential effects of PKC on RIPK4/NF-κB axis and the invasive potential of melanoma cell lines." (PMID 34768934, 2021). "Interestingly, much higher mRNA and protein levels of RIPK4 were observed in the melanoma cells derived from lymph node metastasis (WM266.4) when compared to WM115 cells that were derived from primary melanoma of the same patient." (PMID 34768934, 2021). "Our data show that RIPK4 contributes to melanoma development." (PMID 34768934, 2021).
melanoma (continued). "Collectively, these data indicate the involvement of RIPK4 in determining melanoma invasive potential, but depending on the original level of RIPK4 the extent of these effects might differ." (PMID 34768934, 2021). "Furthermore, we show (iii) the modulatory effect of PKC that differentially influences the impact of RIPK4/NF-κB axis on the invasive potential of melanoma cell lineages." (PMID 34768934, 2021). "However, together with the relatively low RIPK4 levels in the biopsies of prospectively malignant melanoma tumors, they also indicate the stage-specific function of RIPK4 in melanoma development." (PMID 34768934, 2021). "Thus, our results indicate that RIPK4 is involved in melanoma cell invasiveness by influencing cell adhesion and actin dynamics." (PMID 34768934, 2021). "Therefore, we hypothesised that altering RIPK4 expression impairs NFκB and Wnt/β-catenin pathways, also known to regulate chemoresistance and recurrence and increase the sensitivity of melanoma cells to CisPt treatment." (PMID 39766280, 2024). "Although previous studies have indicated the involvement of RIPK4 in adhesion, migration, differentiation, and genes associated with inflammatory processes, these have not been demonstrated specifically in melanoma." (PMID 38656555, 2024). "To assess the mechanisms of the RIPK4-mediated regulation of cell proliferation in melanoma, we examined whether downregulation of RIPK4 affects the levels of important proteins involved in cell cycle regulation, that is, the cyclin-dependent kinases and retinoblastoma protein (RB1)." (PMID 36765875, 2023). "Thus, we suggest that decreasing RIPK4 could potentially restrain melanoma growth as well by inhibiting the AKT-mTOR pathway via FAK." (PMID 36765875, 2023). "PKC) may also determine the recruitment of RIPK4-depressed cells to the invasive melanoma front." (PMID 34768934, 2021). "We demonstrated that the overexpression of RIPK4 inhibits, while its downregulation enhances, CisPt- or DOX-induced apoptosis in melanoma cells." (PMID 39766280, 2024). "In this study, we have found that downregulation of RIPK4 using two different techniques, siRNA and CRISPR/Cas9, inhibits IL-8 and IL-6 production in two melanoma cell lines, WM266.4 and A375." (PMID 38656555, 2024). "To confirm that RIPK4, through the regulation of ABCG2 expression, is crucial for the sensitivity of melanoma cells to CisPt and DOX treatment, we conducted RIPK4 overexpression in A375 cells." (PMID 39766280, 2024). "We generated two melanoma cell lines, WM266.4 and A375, with confirmed RIPK4 knockout (RIPK4.KO) along with their respective control cells (Neg.GFP)." (PMID 38656555, 2024). "However, whether downregulation of RIPK4 can serve as a promising therapeutic strategy to overcome resistance to CisPt or DOX in mul-targeted melanoma chemotherapy requires further investigation on a broader panel of melanoma cell lines and preclinical models." (PMID 39766280, 2024). "The RIPK4 and PEBP1 protein in melanoma cell lines were compared to the levels in normal melanocytes." (PMID 36765875, 2023). "To estimate the significance of PKC signaling for RIPK4 activity in WM266.4 cells and its consequences for cell motility, we treated melanoma cells with 150 nM phorbol-12-myristate-13-acetate (PMA)." (PMID 34768934, 2021). "Incubation of melanoma cells with phorbol ester (PMA) increased PKC-1β level and hyperphosphorylation of RIPK4 resulting in degradation of RIPK4." (PMID 34768934, 2021). "We investigated interactions between RIPK4, PKC and NF-κB pathways in melanoma and the role of RIPK4 in regulating the invasive potential of melanoma cells." (PMID 34768934, 2021). "Thus, RIPK4 might play a pivotal role in the formation of a melanoma invasive front." (PMID 34768934, 2021). "In nonmelanoma skin cancer, RIPK4 plays a suppressor role, whereas in melanoma, it functions as an oncogene that modulates key signalling pathways involved in melanoma cell survival and expansion." (PMID 41660747, 2026).
melanoma (continued). "Treatment with 1,25- D3 of RIPK4.KO cells, compared to their wild-type counterparts, significantly reduced proliferation in 2D and 3D culture (MTT or ATP assay) and decreased p-p65 and cyclin D1 levels in melanoma cells." (PMID 40490050, 2025). "So far, there have been no studies that explain the mechanism of RIPK4 involvement in the resistance of cells to CisPt in melanoma." (PMID 39766280, 2024). "In contrast to pancreatic cancer, melanoma RIPK4 appears not to be a component of the BRAF/MEK/ERK cascade signalling pathway." (PMID 39766280, 2024). "Silencing of RIPK4 through siRNA or knockout via the CRISPR-Cas9 system does not induce apoptosis in melanoma cells." (PMID 39766280, 2024). "It confirms that RIPK4 does not affect the PEBP1/RIPK4 axis or the BRAF/MEK/ERK pathway in melanoma." (PMID 36765875, 2023). "In summary, RIPK4 kinase does not directly affect signal transduction through the BRAF/MEK/ERK pathway in melanoma." (PMID 36765875, 2023). "Although downregulation and upregulation of RIPK4 does not affect signal transduction through the BRAF/MEK/ERK pathway in melanoma, it can inhibit cell proliferation and the FAK/AKT pathway." (PMID 36765875, 2023). "Silencing of RIPK4 in melanoma cell lines had no impact on apoptosis or necroptosis induction but reduced phosphorylation of Akt." (PMID 38139812, 2023). "The results obtained in the present study indicate that the observed reduction in the proliferation rate of melanoma cells under the downregulation of RIPK4 kinase is not related to the targeting of these cells into the necroptosis or apoptosis." (PMID 36765875, 2023). "RIPK4 is a key element of the Wnt/b-catenin signaling pathways or PKC/NFkappaB signaling pathways, which are important for melanoma cell biology and may therefore serve as a ‘bypass’ mechanism for drug resistance." (PMID 36765875, 2023). "The possible role of RIPK4 in the regulation of invasive potential of melanoma was suggested by the current findings by the high RIPK4 levels in metastatic (DMBC21, DMBC28, DMBC29, WM266.4) melanoma cell lines." (PMID 34768934, 2021). "Despite the role of RIPK4 in skin homeostasis, its function in melanoma progression has not yet been investigated." (PMID 34768934, 2021). "Therefore, the interaction between the RIPK4, PKC and NF-κB pathways is involved in the progression of melanoma." (PMID 34768934, 2021). "While the analysis of microarray data has revealed no straightforward correlation between the stage of melanoma progression and RIPK4 expression in vivo, relatively high levels of RIPK4 are in metastatic melanoma cell lines." (PMID 34768934, 2021). "The receptor-interacting protein kinase 4 (RIPK4) plays an important role in the development and maintenance of various tissues including skin, but its role in melanoma has not been reported." (PMID 34768934, 2021). "In melanoma cells, down-regulation of RIPK4 expression by siRNA or PMA did not completely abolish the expression of EMT markers including Twist-1 and Snail-1 and N-cadherin." (PMID 34768934, 2021). "As their interactions affecting the response to 1,25-D3 in melanoma have not been studied, we tested whether downregulation of RIPK4 affects the sensitivity of melanoma cells to 1,25-D3." (PMID 40490050, 2025). "Furthermore, based on our new findings, it suggests that RIPK4 may play a pivotal role in regulating the expression of IL-8 and IL-6 in response to TNF-α stimulation of melanoma cells." (PMID 38656555, 2024). "Despite this, the role of RIPK4 in response to chemotherapeutics in melanoma has not been reported." (PMID 39766280, 2024). "Since MCL-1 acts as a master regulator of apoptosis in various human malignancies, including melanoma, it is not excluded that a decrease in MCL-1 in WM266.4 cells with RIPK4 silencing may affect their susceptibility to BRAFi." (PMID 36765875, 2023).
melanoma (continued). "However, in conjunction with the lack of correlation between melanoma stage and RIPK4 expression levels in ex vivo melanoma biopsies, these data also indicate the complexity of the consequences of RIPK4-dependent signaling for this process." (PMID 34768934, 2021). "Therefore, we further investigated whether ABCG2 downregulation, modulated by the absence of RIPK4, enhances the sensitivity of melanoma cells to doxorubicin." (PMID 39766280, 2024). "Additionally, treatment of wild-type melanoma cells simultaneously with CsA and CisPt or CsA and DOX increases caspase 3/7 activity and reduces the survival of melanoma cells compared to RIPK4.KO cells, regardless of the melanoma cell lines studied." (PMID 39766280, 2024). "Furthermore, the downregulation and overexpression of RIPK4 did not alter the activity of the BRAF, MEK, or ERK1/2 proteins in any of the melanoma cell lines." (PMID 36765875, 2023).
bladder urothelial carcinoma (8 papers, 2018 to 2023). "In bladder urothelial carcinoma, RIPK4 was shown to exhibit a high level and its silence inhibited the tumor growth and migration of bladder urothelial carcinoma cells via modulating NF-κB pathway." (PMID 35310605, 2022). "Recently, a large number of studies have reported that RIPK4 expressions were distinctly dysregulated in many types of tumors, such as nasopharyngeal carcinoma, osteosarcoma, and bladder urothelial carcinoma cell." (PMID 35310605, 2022). "RIPK4 has also been shown to promote bladder urothelial carcinoma cell aggressiveness by NFκB-induced EMT." (PMID 34768934, 2021). "In bladder urothelial carcinoma (BC), receptor-interacting protein kinase 4 (RIPK4) promotes TRAF2 and subsequent NF-κB signaling pathway, ultimately, promotes BC cell aggressiveness." (PMID 31130821, 2019).
cervical squamous cell carcinoma (8 papers, 2015 to 2023). A squamous cell carcinoma arising from the cervical epithelium. "For example, RIPK4 expression is upregulated in nasopharyngeal, pancreatic, bladder urothelial, and cervical squamous cell carcinoma, and is associated with a poor outcome." (PMID 33742531, 2021). "Furthermore, RIPK4 can also function as a potential diagnostic and independent prognostic biomarker for cervical squamous cell carcinoma." (PMID 34124253, 2021). "Studies have also shown that increased expression of RIPK4 makes the disease of patients with cervical squamous cell carcinoma progress rapidly and produces a poor prognosis." (PMID 34222329, 2021). "Here, we report the potential clinical implication and biological functions of RIPK4 in cervical squamous cell carcinoma (CSCC)." (PMID 26148476, 2015).
bladder cancer (7 papers, 2020 to 2025). "RIPK4 expression has also been shown to promote cancer cell migration and invasion in bladder carcinoma, cervical cancer and pancreatic cancer." (PMID 37688617, 2023). "The authors chose HNTs as the best vehicle for RIPK4 siRNA since they were able to transfect selectively bladder cancer cells in vitro." (PMID 34072513, 2021). "However, in bladder carcinoma cells RIPK4 deletion results in higher levels of β-catenin and RIPK4 overexpression rather correlated with a more mesenchymal phenotype of the cells." (PMID 37688617, 2023). "Natural halloysite nanotube (HNT)–assisted delivery of an active small interfering RNA targeting RIPK4 efficiently inhibited RIPK4 expression in vivo and suppressed bladder cancer tumorigenesis and progression with no adverse effects." (PMID 32923402, 2020). "This however does not exclude the possibility that RIPK4 inhibitors might be of use to treat other tumor types, such as DLBCL, pancreatic or bladder cancer." (PMID 37688617, 2023).